SIRT1 (sirtuin 1)
Diseases named in the same sentence as SIRT1 in open-access papers (continued):
Sharing a sentence is not in itself a finding about the gene and the disease.
atherosclerosis (continued). "Therefore, Sirt1 may be a protective molecule that can break this cycle such that its activation is beneficial in suppressing vascular aging and atherosclerosis." (PMID 27744418, 2016). "Finally, evidence has also accumulated to suggest that SIRT1 activation could be a therapeutic strategy to reverse atherosclerosis." (PMID 27123454, 2016). "Regarding coronary artery disease, several SIRT1 promoter polymorphisms potentially changing the putative transcription binding sites were exclusively present in patients with myocardial infarction, not in the healthy controls without atherosclerosis." (PMID 27104517, 2016). "Thus, Sirt1 may prevent the generation and progression of atherosclerosis by enhancing the LXR-ABCA1/ABCG1/CCR7 pathway to suppress foam cell formation." (PMID 27744418, 2016). "Wang and so forth revealed that SIRT1 inhibits transcription of RelA/p65 subunit by deacetylation of NF-κB and reduces the generation of oxygen free radicals so as to inhibit the main pathological factors which promote atherosclerosis and cardiovascular disease." (PMID 25114706, 2014). "Moreover, and the SIRT1 activator resveratrol has been shown to mediate reduced atherosclerosis." (PMID 24219792, 2013). "Furthermore, calorie/dietary restriction or overexpression of SIRT1 in ApoE-/- mice exhibited an anti-atherosclerosis effect by inhibiting oxidized low-density lipoprotein (LDL)-induced apoptosis, upregulation of eNOS expression and improved endothelium-dependent vasorelaxation." (PMID 20663150, 2010). "Further research is needed to betterunderstand the role of SIRT1 in the development of TAA and aortic dissections,taking into account factors such as collagen production, atherosclerosis, and thespecific segments of the aorta involved." (PMID 41259217, 2026). "It maintains SIRT1 protein levels, upregulates USP22, promotes autophagy and reduces lipid accumulation, leading to a protective effect against atherosclerosis progression." (PMID 41567643, 2025). "Studies have also confirmed that high doses of NR supplementation deteriorated atherosclerosis and induced systemic inflammation in ApoE−/− mice through increasing hepatic expression levels of CD38 and decreasing SIRT1." (PMID 40143060, 2025). "Several recent studies have underscored the pivotal role of Sirtuin-1 (SIRT1) as a regulator in the formation and progression of atherosclerosis." (PMID 40475061, 2025). "Low KL levels seem to be correlated with atherosclerosis, and BBR upregulating SIRT1 also increases KL expression, leading overall to a protective condition." (PMID 41228388, 2025). "Sirtuin 1 (SIRT1) is a class III histone deacetylase involved in vascular metabolism, atherosclerosis, and aging." (PMID 40507889, 2025). "Here, we unveiled boosting circulating SIRT1 levels as a feasible and effective strategy to increase plasma LDL-C clearance and decrease inflammation during atherosclerosis." (PMID 40653676, 2025). "Therefore, SIRT1 may be an attractive therapeutic target for atherosclerosis." (PMID 38202844, 2024). "Resveratrol, the most widely studied natural Sirt1 activator, extends the lifespan of HFD‐fed mice and reduces atherosclerosis formation in ApoEKO mice." (PMID 38818612, 2024). "Building on the established role of ox-LDL in atherosclerosis and its potential to induce damage in HCAEC, our study aims to unravel the intricate relationship between BATF, a transcription factor, and SIRT1, a protective NAD+-dependent protein deacetylase." (PMID 39680523, 2024).
atherosclerosis (continued). "The miR-217 was found to be upregulated in old HUVECs, HAECs, and human coronary artery endothelial cells (HCAECs) and it was demonstrated that miR-217 modulates SIRT1/eNOS and SIRT1/FOXO1 axes to inhibit angiogenesis and promote atherosclerosis." (PMID 38909168, 2024). "The upregulation of SIRT1 and deacetylation of PGC-1α by SRT1720 restores mitochondrial function, inhibiting VSMC senescence and the expression of atherosclerosis-related proteins and phenotypes." (PMID 38999988, 2024). "Taken together, emerging evidence suggests that sirtuin isoforms, particularly SIRT1 and SIRT6, play a protective role against EC senescence and atherosclerosis." (PMID 37894840, 2023). "Among the seven mammalian sirtuins (SIRT1–SIRT7), SIRT1 and SIRT6 have been widely studied in the context of EC senescence and atherosclerosis." (PMID 37894840, 2023). "The expression of sirtuin 1 (SIRT1) is decreased in diseases of accelerated ageing including Alzheimer’s disease, chronic kidney disease, osteoporosis, T2D, metabolic syndrome, COPD, atherosclerosis, and cardiac failure." (PMID 35359598, 2022). "Deacetylation of autophagy protein 5 (ATG5) by SIRT1 activates ATG5 to increase autophagy, which protects from atherosclerosis." (PMID 35529430, 2022). "There are seven mammalian sirtuins, with SIRT1 and SIRT6 investigated with regard to protection against atherosclerosis." (PMID 35569818, 2022). "FOXO1 and its gene expression as well as SIRT1 and HSP72 were suggested as predictors of early detection of premature atherosclerosis, but as far as our knowledge, our team was the first to prove such results in β-TM patients." (PMID 36289866, 2022). "Expression of SIRT1 and SIRT6 is decreased in atherosclerotic plaques, while overexpression of SIRT1 or SIRT6 significantly attenuated oxidized LDL‐ or palmitate‐induced VSMC senescence and inhibited atherosclerosis." (PMID 35569818, 2022). "A lower expression of Sirtuin 1 (SIRT1) leads to ovariectomy (OVX)-induced arterial senescence and atherosclerosis in apolipoprotein E-knockout (ApoE-KO) mice." (PMID 35280995, 2022). "Among all SIRTs, SIRT1 and SIRT6 are characterized for their protective mechanism against inflammation, vascular aging, and atherosclerosis in DM." (PMID 34071497, 2021). "SIRT1, possibly through the AKT and ERK signaling pathways, plays a crucial role in estrogen in protecting arteries from senescence and atherosclerosis." (PMID 33715628, 2021). "Many studies have identified a relationship between reduced SIRT1 activity and the development of CAVD and atherosclerosis." (PMID 34142751, 2021). "Consistent with this, treatment with SIRT1 agonist SRT3025 decreased levels of LDL-cholesterol and diminished atherosclerosis in Apoe(-/-) mice." (PMID 33114351, 2020). "SIRT1 dysfunction and YAP activation were found in areas of the vasculature that are normally prone to atherosclerosis." (PMID 32081881, 2020). "NF-kB, SIRT1 and systemic inflammation factors including hs-CRP, IL-6 and TNF-α accelerate atherosclerosis pathogenesis." (PMID 31901246, 2020). "It has been found that chlorogenic acid can mitigate ox-LDL-induced endothelial oxidative stress and mitochondrial dysfunction by modulating the SIRT1/AMPK/PGC-1 pathway, thus providing beneficial effects in atherosclerosis." (PMID 32566106, 2020). "Downregulation of SIRT1 and NAD+ was observed during aging, due to age-related atherosclerosis, presumably resulting from impaired eNOS activity." (PMID 32796661, 2020). "However, SIRT1 also activates other components of the BER pathway, including the enzymes thymine DNA glycosylase, apurinic/apyrimidinic endonuclease 1, and poly(ADP-ribose) polymerase 1,48,49 which may partly explain the profound effect of VSMC SIRT1 knockout in atherosclerosis." (PMID 29643057, 2018). "SIRT1, a highly conserved NAD+-dependent protein deacetylase, plays a pivotal role in the pathogenesis and therapy of atherosclerosis (AS)." (PMID 28881659, 2017).
atherosclerosis (continued). "However, previous reports have shown that reduced Sirt1 expression in isolated monocytes or mononuclear cells from human subjects may be related to systemic or possibly vascular wall inflammation, which contributes to atherosclerosis." (PMID 27744418, 2016). "Therefore, Sirt1 may exert protective effects against vascular aging and atherosclerosis." (PMID 27744418, 2016). "SIRT1, an NAD(+)-dependent class III histone deacetylase, was also discovered to suppress LOX-1 expression, thus playing a protective role in atherosclerosis." (PMID 25247304, 2014). "Therefore, Sirt1 may serve as a novel therapeutic target for the treatment of atherosclerosis." (PMID 24378473, 2014). "A number of enzymes participate in processes that protect arteries from atherosclerosis, including P450-enzymes belonging to different cytochrome (CYP) classes, CCTα, sirtuin 1(SIRT1) and paraoxonase-1 (PON1)." (PMID 20604930, 2010). "Unlike its well-characterized role in atherosclerosis, SIRT1 exerts multifaceted protective effects directly on cardiac tissue." (PMID 42196199, 2026). "SIRT1 knockdown blocks the SIRT1/NRF2/GPX4 pathway, exerting a protective effect against lipid accumulation, suggesting that SIRT1 could be a viable target for atherosclerosis." (PMID 40099271, 2025). "In addition to SIRT1, SIRT6 has been recognized for its protective roles against inflammation, vascular aging, heart disease, and atherosclerosis." (PMID 39769085, 2024). "SIRT1 activation by resveratrol inhibits the TLR4-mediated inflammatory response in ox-LDL-activated platelets, thus likely contributing to the treatment of thrombosis and atherosclerosis." (PMID 38304233, 2023). "In 2010, SIRT1 was emerged as a crucial player in the regulation of tissue metalloproteinase 3 (TIMP3), an endogenous enzyme with a role in vascular inflammation and preventing atherosclerosis." (PMID 38304233, 2023). "Therefore, quercetin play an important role in the treatment of atherosclerosis by preventing endothelial cell damage via SIRT1/AMPK/Nrf2 mediated oxidative stress, SIRT1/PI3K/Akt/NF-κB and SIRT1/TLRs/MAPK mediated inflammatory response." (PMID 35935939, 2022). "Sirtuin 1 (SIRT1) plays an additional protective role in vascular biology and atherosclerosis." (PMID 34136191, 2021). "The functional regulation of SIRT1 and TFEB by berberine could be exploited as a potential therapeutic strategy for atherosclerosis." (PMID 33639613, 2021). "Moreover, it has been reported that miR-188 inhibits cyclin-dependent kinase 5 (CDK5) gene expression, which is a strong regulator of sirtuin 1 (SIRT1), which acts on cellular senescence and the development of atherosclerosis." (PMID 32903262, 2020). "In summary, SIRT1 and autophagy can limit YAP activation to prevent atherosclerosis." (PMID 32081881, 2020). "Until now, the roles of SIRT1 and FOXO1 in atherosclerosis as therapeutic target remain largely unknown." (PMID 31146723, 2019). "Sirtuin 1 (SIRT1), a class III histone deacetylase, may protect against vascular aging and atherosclerosis; however, the effects of estrogen on SIRT1 expression and vascular smooth muscle cell (VSMC) behavior remain unknown." (PMID 29299128, 2017). "SIRT1, a class III histone deacetylase, regulates multiple cellular functions, and may slow the development of atherosclerosis." (PMID 29299128, 2017). "Therefore, the Sirt1-LXR-ABCA1/ABCG1 signaling pathway is involved in the regulation of cholesterol efflux and is inhibited during the initiation and progression of atherosclerosis, resulting in cholesterol uptake by macrophages and foam cell formation." (PMID 27744418, 2016). "Besides, SIRT1 activation can inhibit vascular smooth muscle cell (VSMC) hypertrophy, which has been considered one of the critical contributors to atherosclerosis." (PMID 25706717, 2015).
atherosclerosis (continued). "The genetic effect of SIRT1 and FOXO1 on common carotid IMT shown in the current study might be explained by their direct involvement in the pathophysiological mechanisms of atherosclerosis." (PMID 25273948, 2014). "These preclinical studies provide biochemical evidence that the dysregulation of SIRT1-AMPK-SREBP pathway and stimulation of NLRP3 inflammasome and IL-1β production may coordinately contribute to the initiation and progression of atherosclerosis." (PMID 23825667, 2013). "These translational studies provide in vivo evidence that the dysregulation of SIRT1-AMPK-SREBP and stimulation of NLRP3 inflammasome may contribute to vascular lipid deposition and inflammation in atherosclerosis." (PMID 23825667, 2013). "In addition, a novel DPP-4 inhibitor anagliptin, was investigated as a potential therapeutic in atherosclerosis, and its treatment improved TNF- α, IL6, and MCP-1 secretion in VSMC, reduced telomerase activity, and reversed upregulated SIRT1 in IL-1 β treated cells." (PMID 41567643, 2025). "Furthermore, in human aortic endothelial cells and serum from ApoE−/− mice, Mito-Esc activated the metabolic and stress-sensing autophagy regulator, SIRT1, altered miR-19b and miR-30c and significantly inhibited plasminogen activator inhibitor-1 (PAI-1), a key mediator of atherosclerosis." (PMID 41300435, 2025). "As the SIRT1 small molecule activator with oral activity, SRT3025 increases the expression of hepatic LDL receptors and accumulation of proprotein convertase subtilisin/kexin type 9 (Pcsk9), reduces plasma cholesterol level, inhibits inflammatory response and atherosclerosis." (PMID 36632457, 2023). "In the experimental model, it was established that SIRT1 regulates autophagy and apoptosis of ischemic cardiomyocytes by activating AMP-activated protein kinase (AMPK) and also suppresses the production of foam cells and, thereby, prevents the progression of atherosclerosis." (PMID 38139440, 2023). "In addition, the activation of NF-kB signaling pathway inhibits the anti-inflammatory pathway, Sirtuin 1 (SIRT1) signaling pathway, which is closely related to the development of non-infectious chronic diseases such as atherosclerosis and DKD." (PMID 35874522, 2022). "In addition, SIRT1 and SIRT6 also alleviated senescence in ECs and EPCs, suggesting a protective role in modulating atherosclerosis." (PMID 35569818, 2022). "Interestingly, SIRT1 also relies upon AMPK for the regulation of insulin sensitivity and to induce autophagy that is necessary for endothelial cell protection during exposure to oxidized low density lipoproteins that can lead to atherosclerosis." (PMID 26064426, 2015). "Because the integrated suppression of vascular SIRT1 and AMPK have an impact on activation of SREBP in arterial atherosclerosis, our findings highlight the rationale for targeting SIRT1-AMPK–SREBP signaling as a potential therapeutic treatment of human atherosclerosis." (PMID 23825667, 2013). "Hence, SIRT1 activation (and NAD+ replenishment) may not only activate eNOS but will also inhibit endothelial cell senescence, atherosclerosis and inflammatory response in the lung." (PMID 20663150, 2010).
atherosclerosis (continued). "The authors of this study suggested that the carriers of those genotypes might have reduced activity of SIRT1 and therefore decreased activity of LXR (protecting the organism from cholesterol overload, reducing cholesterol loading in macrophages, and protecting from atherosclerosis)." (PMID 27104517, 2016). "Our findings may have implications regarding the influence of defective autophagy on cell survival and the expression of Sirt1 in atherosclerosis, since the cell status was poor and the level of Sirt1 was not elevated when the cells were incubated with 3-MA + 12.5 μM RSV." (PMID 24378473, 2014). "Compared with SIRT1, the influence of SIRT2 on VC has not been thoroughly investigated; however, in recent years, several studies on SIRT2 and atherosclerosis have been reported." (PMID 35677446, 2022). "While we did not observe a relationship between SIRT1 expression and the severity of coronary lesions in patients with both CAD and T2DM, the exact role of SIRT1 in atherosclerosis is more profound than most studies reported." (PMID 27123454, 2016). "SIRT1, a class III histone deacetylase, acts as a negative regulator for many transcription factors, and plays protective roles in inflammation and atherosclerosis." (PMID 24859347, 2014).